TREM2 (triggering receptor expressed on myeloid cells 2)
Diseases named in the same sentence as TREM2 in open-access papers (continued):
Sharing a sentence is not in itself a finding about the gene and the disease.
neurological diseases (34 papers, 2013 to 2025). "Although TREM2 is almost exclusively expressed on microglia and TREM2 variants are associated with neurological disease, the impact of TREM2 on CNS function is still under debate." (PMID 29040522, 2018). "TREM2 mutations are associated with neurological disorders, although it is not well known how TREM2 contributes to these diseases." (PMID 28149270, 2016). "Emerging therapeutic approaches focus on modulating the TREM2 pathway as a potential therapeutic target for neurological disorders." (PMID 41476737, 2025). "Recently, TREM2, a key lipid sensor in microglia, has emerged as a crucial player in AD and other neurological diseases." (PMID 40242752, 2025). "Several CSF molecules have been proposed as reliable markers for glial cell activation within CNS, potentially reflecting the involvement of astrogliosis (i.e. GFAP) and microgliosis (i.e. soluble TREM2) in the pathogenesis of neurological disorders." (PMID 38142915, 2024). "Triggering receptor expressed on myeloid cells 2 (TREM2) plays an essential role in microglia activation and is being investigated as a potential therapeutic target for modulation of microglia in several neurological diseases." (PMID 39431020, 2024). "TREM2 is expressed specifically by microglia in the CNS, which is believed to be crucial for the clearance of tissue debris in homeostasis and during neurologic diseases." (PMID 37013543, 2023). "This is supported by several studies reporting an important role of Trem2 and Lrp1 in phagocytosis and neuroprotection in neurological disease." (PMID 38155863, 2023). "Soluble triggering receptor expressed on myeloid cells 2 (sTREM2) in cerebrospinal fluid (CSF) has been described as a biomarker for microglial activation, which were observed increased in a variety of neurological disorders." (PMID 35382840, 2022). "Recently, several studies have revealed that TREM2 is involved in the inflammatory pathology of a variety of neurological disorders." (PMID 32617097, 2020). "Recently, the triggering receptor expressed on myeloid cells 2 (TREM2) expressed by microglia was identified as a critical factor of inflammation in nervous system diseases." (PMID 33081801, 2020). "Our current study showed that applying either JNK or NF-κB inhibitor restored Trem2 expression down-regulated by LPS, implicating a potentially beneficial effect of those inhibitors for treating neurological diseases with an inflammatory component." (PMID 28680398, 2017). "In addition to AD, TREM2 exerts significant neuroprotective effects in various neurological diseases." (PMID 40242752, 2025). "TREM2 (triggering receptor expressed on myeloid cells 2) is an immune receptor expressed by microglia, and its shedded soluble form (sTREM2) has been investigated as a potential biomarker of microglia activity in neurological disease." (PMID 39030984, 2024). "Studies in AD and other neurological diseases have examined the impact genetic ablation of TREM2 may have with respect to neuroinflammation and neurological decline." (PMID 34369386, 2021). "Animal and human genetic studies have demonstrated that microglia without TREM2 or with mutated TREM2 do not convert to an activated stage and subsequently lead to development and/or progression of neurologic disorders." (PMID 35185751, 2021). "Taken together, our results provide a novel molecular link between TREM2 and CELF proteins and reveal a species-specific difference of TREM2 that may be important for the disease modeling of AD and other neurological diseases involving microglia and TREM2." (PMID 33093587, 2020). "Taken together, TREM2 may be an upstream regulator of inflammation in a variety of neurological disorders." (PMID 32617097, 2020). "However, there are still not enough studies on pharmacological agents that modulate TREM2 directly, making it difficult to understand the functionality of TREM2 and its precise association with neurological disorders." (PMID 41488618, 2025).
neurological diseases (continued). "Thus, TREM2 and CSF1R are considered crucial molecules for “microgliopathy”, which is characterized by reactive gliosis and microglia dysfunction and has been recently proposed as the neuropathological hallmark of neurological disorders." (PMID 33841415, 2021). "Triggering receptor expressed on myeloid cells-2 (TREM2) and colony-stimulating factor 1 receptor (CSF1R) are crucial molecules for microgliopathy, which is characterized by microglia dysfunction and has recently been proposed as the neuropathological hallmark of neurological disorders." (PMID 33841415, 2021). "TREM2 agonists and inhibitors of the PI3K/AKT signaling pathway are being explored as potential therapeutic strategies for neurological disorders." (PMID 39758888, 2024). "We chose Alox5ap and Laptm5 to illustrate that expression profiles for the microglial gene module were similar irrespective of whether a gene has an established role in neurologic disease (e.g., Trem2 and Alox5ap) or limited to no known role (e.g., Laptm5) in neurologic disease." (PMID 31214167, 2019).
metabolic disease (24 papers, 2020 to 2026). A congenital disorder (due to inherited enzyme abnormality) or acquired (due to failure of a metabolically important organ) disorder resulting from an abnormal metabolic process. "Genetic factors including APOE4 and TREM2 variants affect microglial lipid handling pathways, while systemic metabolic disorders and gut microbiota alterations amplify neuroinflammatory cascades." (PMID 42194007, 2026). "Moreover, TREM2 has been implicated in cancer and metabolic disorders, where it influences tumor immune evasion and adipose tissue homeostasis." (PMID 41356595, 2025). "Recently, TREM2 signaling in macrophages has been linked to metabolic diseases." (PMID 39113887, 2024). "Accumulating evidence suggests that Trem2+ macrophages represent a specialized regulatory subset particularly relevant in fibrosis, neuroinflammation, and metabolic diseases." (PMID 41356595, 2025). "TREM2 expressed by macrophages inhibits the development of metabolic disorders by facilitating cell death of prone adipocytes." (PMID 36814909, 2023). "However, recent studies on metabolic disorders have suggested that CD9 and TREM2 are markers of lipid-associated macrophages (LAMs) that produce proinflammatory cytokines in humans." (PMID 36814909, 2023). "Interestingly, several studies have found that NAFLD is also a type of metabolic disease that can be regulated by TREM2." (PMID 35658903, 2022).
bone cysts (19 papers, 2013 to 2025). "In NHD, mutations in TREM2/DAP12 cause bone disorder followed by brain phenotype." (PMID 33568650, 2021). "Homozygous loss-of-function mutations in TREM2 or DAP12 genes cause Nasu–Hakola disease (NHD), a rare genetic disorder characterized by fatal presenile dementia and bone cysts." (PMID 32772264, 2020). "Generally, TREM2 is appreciated for its expression on the surface of cells in the monocyte-macrophage lineage, such as microglia and osteoclasts, with implications for neurodegenerative diseases and bone disorders." (PMID 36119485, 2022). "In addition to these 3 Turkish cases, 2 other families were also reported to carry homozygous mutations in TREM2, presenting with a bvFTD-like phenotype without bone cysts." (PMID 23870839, 2013).
bacterial infection (13 papers, 2014 to 2025). "The fraction of dead cells (PI+) was significantly higher in KO than WT BMDMs, indicating that deficiency of TREM2 promotes macrophage death after pyogenic bacterial infection." (PMID 36068223, 2022). "There was also decreased neutrophil recruitment to mouse lungs in response to bacterial infection in TREM2 deficient mice." (PMID 28768545, 2017). "TREM2 variant carriers may also have increased risk of systemic infection and TREM2 deficiency is detrimental in the context of bacterial infection." (PMID 28768545, 2017). "TREM2 activates different signaling pathways in response to bacterial infection, which will be described in detail below." (PMID 38236825, 2024). "During bacterial infection, TREM2 has a tendency to promote macrophage transformation to M2 type and alters macrophage cytokine production." (PMID 38236825, 2024). "The role of TREM2 in promoting the anti-inflammatory phenotype of macrophages during bacterial infection is unclear." (PMID 38236825, 2024). "Triggering receptors expressed on myeloid cells 2 (TREM2) is considered a protective factor to protect host from bacterial infection, while how it elicits this role is unclear." (PMID 36068223, 2022). "Past studies have shown a conflicting role for TREM2 in regulating ROS production in different bacterial diseases." (PMID 35924849, 2022). "To exploit the functional role of this constitutive pulmonary TREM-2 expression in relation to early pulmonary inflammatory responses following bacterial infection, we next infected WT and Trem-2−/− mice with S. pneumoniae for 6 h." (PMID 24945405, 2014). "Importantly, the source of intracellular ROS production mediated by TREM2 is not clear, and identifying the source of intracellular ROS after bacterial infection is helpful to study the regulatory role of TREM2 on ROS." (PMID 38236825, 2024). "However, the role of TREM2 in regulating ROS production in different bacterial diseases is contradictory." (PMID 38236825, 2024). "Indeed, consistent with our in vivo data, studies with WT and Trem2−/− BMDMs have reported an inherent hyperinflammatory phenotype of Trem2−/− BMDM in response to LPS as well as an increased NLRP3 activation in the context of bacterial infection and neuro-inflammation (28, –30)." (PMID 39172787, 2024). "However, in spite of the capability of TREM-2 to bind to bacteria, neither humans nor mice deficient in TREM-2 show increased susceptibility to bacterial infection, suggesting the occurrence of other mechanisms in host defense." (PMID 31546668, 2019). "TREM2 conducts signal through DNAX-activating protein of 12 kDa (DAP12), negatively modulating inflammatory response during bacterial infection." (PMID 36068223, 2022). "Since pyroptosis is often associated with inflammasome activation, we further tested the role of TREM2 on the activation of NLRP3 and NLRC4 inflammasome, which have been reported as the major inflammasomes induced by pyogenic bacterial infection." (PMID 36068223, 2022). "Moreover, while TLR4 remained up-regulated upon LPS treatment, TREM2 was downregulated, suggesting that LPS–TLR4 interaction during bacterial infections could down-regulate the anti-inflammatory action of TREM2." (PMID 38299364, 2024).
infectious disease (7 papers, 2014 to 2024). A disorder directly resulting from the presence and activity of a microbial, viral, or parasitic agent in humans. "TREM-1 and TREM-2, the best-characterized receptors so far, play divergent roles in several infectious diseases." (PMID 25347935, 2014). "The in vivo role of TREM-2 in infectious diseases remains ill defined." (PMID 27253382, 2016).
inflammation (5 papers, 2017 to 2024). Aberrant reaction of the microcirculation characterized by movement of fluid and leukocytes from the blood into extravascular tissues. "We also observed similar divergent Trem1 and Trem2 responses in vivo in response to acute brain inflammation and acute cerebral ischaemia." (PMID 28303091, 2017). "Since expression of TREM2 and Gal3 are features of disease-associated microglia (DAM);, we may conclude that nigral microglia get activated after acute gut inflammation but they acquire a phenotype different from classical DAM." (PMID 34483912, 2021). "Overall, these data suggest that resolution of acute brain inflammation is associated with induction and/or restoration of “homeostatic” microglial signature genes and a transition in the balance of amplifying and modulatory immune signaling via immunoreceptors such as TREM1 and TREM2." (PMID 31156629, 2019).
brain diseases (4 papers, 2021 to 2024). "Targeting at the role of TREM1 and TREM2 in brain structure and brain diseases, many investigations have been conducted, and the results showed that the protein expression of TREM1 and TREM2 in the hippocampus and PFC could be altered by age or inflammatory stimulants." (PMID 34789244, 2021).
cardiovascular disease (4 papers, 2022 to 2025). "The overall aim of this review is to highlight the various roles of TREM2 in cardiovascular diseases and to provide a framework for therapeutic strategies targeting TREM2." (PMID 40083551, 2025). "Recent research has indicated that TREM2 signaling is also activated in various cardiovascular diseases." (PMID 40083551, 2025). "As the hub of pathological immune signaling, TREM2 is an attractive therapeutic target for cardiovascular disease." (PMID 40083551, 2025). "Summary of previous studies on the role of triggering receptor expressed on myeloid cells 2 (TREM2) in specific diseases, including cardiovascular disease." (PMID 36982629, 2023). "Additionally, we discuss the clinical significance of elevated soluble TREM2 (sTREM2) in cardiovascular disease and propose potential therapies targeting TREM2." (PMID 40083551, 2025). "This suggests that targeting microglial TREM2 may represent a promising therapeutic approach for cardiovascular diseases." (PMID 40083551, 2025). "Nonetheless, the involvement of TREM2 in cardiovascular disease has not been thoroughly explored." (PMID 40083551, 2025).
gastrointestinal tumors (4 papers, 2019 to 2024). "We also detected the TREM2 expression patterns in other gastrointestinal tumors and found various expression patterns of TREM2." (PMID 30683932, 2019). "Corroborating observations that TREM-2 attenuated chronic liver injury, elevated transaminases were observed in Trem-2-/- mice reconstituted with Trem-2-/- BM compared with WT." (PMID 29374630, 2019). "The dogmatic view is that macrophage Trem2 suppresses inflammation and protects the liver from injury, but this is contrary to our findings because blocking myeloid-derived Trem2 early in the induction of inflammation alleviates liver IR injury." (PMID 37047321, 2023). "In addition, we explored TREM2 expression patterns in other gastrointestinal tumors." (PMID 30683932, 2019). "Since monocytes are recruited to the liver in response to liver IR injury and participate in the complex process of regulating pro-inflammatory and anti-inflammatory activities, we speculate that targeting myeloid Trem2 may play an irreplaceable role in this process." (PMID 37047321, 2023).
immune dysfunction (4 papers, 2013 to 2025). "Given the similarities in Aβ accumulation between the two regions it seems that disease-specific immune dysfunction may be more related to tau pathology as has been reported elsewhere for TREM2 and MS4A6A43." (PMID 33649380, 2021).
cardiac diseases (3 papers, 2023 to 2025). "Previous studies have highlighted the anti-apoptotic and immunomodulatory functions of TREM2, especially in neurodegenerative and cardiac diseases; however, its role in radiation-induced apoptotic signaling has not been clearly delineated." (PMID 41356595, 2025). "Our study highlights that maintaining the function of this subset by harnessing TREM2 could be a potential therapeutic strategy for cardiac diseases in clinic." (PMID 36635449, 2023).
central nervous system disease (3 papers, 2016 to 2025). "Collectively, these results not only suggest that microglial lysosomal autophagy is regulated in a TREM2-dependent LMP manner, but also, more importantly, they provide a promising clinical translation strategy based on gene therapy for lysosome-related central nervous system disorders." (PMID 40320759, 2025).
neurodevelopmental disorder (3 papers, 2024 to 2025). A behavioral and cognitive disorder with onset during the developmental period that involves impaired or aberrant development of intellectual, motor, or social functions. "However, given the key role of microglia in neurodevelopment and reported cases of TREM2 variants in patients with neurodevelopmental disorders, further investigations into the potential contribution of TREM2 dysregulation, including LoF mutations, to ASD or related phenotypes are warranted." (PMID 41476737, 2025). "This knowledge is vital for understanding TREM2‐dependent DAM and its involvement in the pathogenesis of neurodevelopmental disorders which can help to develop targeted therapies and improve outcomes for TREM2‐affected individuals." (PMID 38888203, 2024).
psychiatric disorder (3 papers, 2013 to 2024). A disorder characterized by behavioral and/or psychological abnormalities, often accompanied by physical symptoms. "TREM2 expression in leukocytes may be a novel biomarker for neurological and psychiatric disorders." (PMID 26332043, 2015). "Further studies of the TREM2/TYROBP signaling should be performed to elucidate its role in neurological and psychiatric diseases." (PMID 26332043, 2015).
kidney disease (2 papers, 2023 to 2025). "In conclusion, our study not only provides mechanistic insights into the role of Trem2 in regulating macrophage‐mediated inflammation and fibrosis in kidney injury but also opens a new avenue for macrophage‐based cell therapy to treat kidney diseases." (PMID 40000418, 2025). "Our study not only provides valuable mechanistic insights into the role of Trem2 in the AKI–CKD transition but also offers a new avenue for TREM2‐overexpressing macrophage‐based adoptive cell therapy to treat kidney diseases." (PMID 40000418, 2025). "This is the first study to demonstrate the translational potential of TREM2‐overexpressing macrophage‐based cell therapy in the treatment of kidney disease." (PMID 40000418, 2025). "Studies have suggested that TREM2 may be involved in regulating inflammatory responses and cellular stress responses in kidney disease." (PMID 40000418, 2025). "In conclusion, our study not only provides valuable mechanistic insights into the role of Trem2 in regulating macrophage‐mediated inflammation and fibrosis in the AKI–CKD transition but also offers a new avenue for TREM2‐overexpressing macrophage‐based cell therapy to treat kidney diseases." (PMID 40000418, 2025).
movement disorder (2 papers, 2020 to 2024). Neurological conditions resulting in abnormal voluntary or involuntary movement, which may impact the speed, fluency, quality and ease of movement. "Myelin basic protein (MBP) and the soluble form of TREM2 were quantified in a comprehensive movement disorder cohort from two different neurological centers, comprising a total of 171 CSF samples." (PMID 39666067, 2024). "The present study reports on the quantification of myelin basic protein (MBP) and soluble triggering receptor expressed on myeloid cells 2 (TREM2) in the CSF of a comprehensive movement disorder cohort." (PMID 39666067, 2024). "Taken together, these results indicated that the learning and memory function was significantly attenuated in the 5xFAD-AAV-TREM2 (TREM2-lack) group without movement disorder and anxious behaviors." (PMID 33065553, 2020).
vasculopathy (1 paper, 2022). "In addition, our results revealed the microvascular profile that favors the disease phenotype of microglial mirrored in the upregulation of TYROBP, TREM2, and Cst7 in both early and late stages of CAA vasculopathy." (PMID 35813502, 2022).